TNF (tumor necrosis factor)
Diseases named in the same sentence as TNF in open-access papers (continued):
Sharing a sentence is not in itself a finding about the gene and the disease.
mastitis (continued). "Previous studies have shown that through the activation of the NF-κB signaling pathway, miR-142 induces the release of cytokines such as TNF-α, IL-1β, IL-6, and IL-8, suggesting its pro-inflammatory role in the mastitis process." (PMID 40001538, 2025). "Several studies have reported that the levels of TNF-α, IL-1β, IL-6, and IL-8 in dairy cows with mastitis increase." (PMID 40266913, 2025). "Some studies have demonstrated that the fecal microbiota of cows with mastitis can be transferred to germ-free mice, which then exhibit mastitis and serum inflammation [increased TNF-α, interleukin-17 (IL-17), LPS levels]." (PMID 40552082, 2025). "TNF-α increased the secretion of IL-6 and other cytokines and exacerbated mastitis-induced tissue damage through excess ROS." (PMID 38630770, 2024). "The clinically explored KDM1A inhibitor GSK-LSD1 has been reported to inhibit the NF-κB-dependent production of cytokines (TNFα, IL-6, IL-1) by increasing histone H3K4me2 and H3K9me2 in LPS-induced mastitis." (PMID 39638799, 2024). "Gambogic acid (GA) was also reported to alleviate LPS-induced mastitis by reducing IL-6, TNF-α, and IL-1β levels." (PMID 39199398, 2024). "In general mastitis cases, immunoreactivity was more pronounced for IL-4, IL-6, IL-12, IL-13, IL-17A, TNF-α, and IFN-γ." (PMID 39195804, 2024). "To explore the inflammatory and immune status between healthy and mastitis cows, we next performed serum TNF-α, IL-8, IL-6, IL-1, and LPS tests and found that mastitis cows had higher (p < 0.05) serum TNF-α, IL-1, and LPS concentration." (PMID 38585704, 2024). "Previous studies have also reported greater concentrations of IL-1β and TNFα in milk from mastitis-affected women." (PMID 39896819, 2024). "Elevated SFA levels can activate the Toll-like receptor (TLR) 4 signaling pathway, leading to the increased production of pro-inflammatory cytokines, such as tumor necrosis factor-alpha (TNF-α) and IL-6, thereby promoting the onset of mastitis." (PMID 39684757, 2024). "Cows with mastitis exhibit higher concentrations of TNF-α and IL-1 in their blood, consistent with previous studies." (PMID 38585704, 2024). "Five mastitis-related pathways were found, including the signaling pathways for TNF, MAPK, PI3K-Akt, and IL-17." (PMID 38630770, 2024). "Increased levels of TNF-α and IL-1β in subclinical mastitis were discovered in this study, suggesting that they play a role in the early stages of mastitis development." (PMID 36899749, 2023). "Data about subclinical and clinical mastitis demonstrate inflammatory responses to the intramammary infection driven by IL-1β, IL-6, and TNF-α." (PMID 36899749, 2023). "TNF‐α and IL‐1β are important inflammatory cytokines that play critical role in the development of mastitis." (PMID 37328960, 2023). "The pro-inflammatory cytokines IL-12, IL-6, TNF-α, and IL-1β were found to be significantly elevated in lactating cows suffering from clinical mastitis." (PMID 36899749, 2023). "The expression of TNF-α was significantly lower in mice in the lipopeptide-treated group compared with those in the mastitis-untreated group." (PMID 37189805, 2023). "Several studies have showed that the modulation of ERK and MAPK signaling pathway can lead to anti-inflammatory role in mastitis due to the decreased release of pro-inflammatory cytokines such as tumor necrosis factor-α, IL-1β, and IL-6." (PMID 37016420, 2023). "TNF-α and IL-6 are immunoreactive in cases of mastitis, while IL-1α of the IL-1 family is more capable of driving the corresponding inflammatory response." (PMID 37189805, 2023). "Proinflammatory cytokines including TNF‐α and IL‐1β are closely related to the development and progression of mastitis." (PMID 37644785, 2023). "When PUE was added to the dairy diet of the healthy cows and cows with mastitis, the levels of TNF-α, IL-1β, and IL-6 in the whey of the cows on day 7 were significantly lower than those on day 0 (p < 0.01)." (PMID 37175449, 2023).
mastitis (continued). "The serum TNF-α, IL-1β, and IL-6 levels of the cows with mastitis fed PUE root on day 7 were significantly lower than those on day 0 (p < 0.01), but there was no change in the healthy cows after the 7th day of the PUE addition." (PMID 37175449, 2023). "The Exosome Inc‐AFTR has the potential to exert anti‐inflammatory and antiapoptotic effects on mastitis cells MAC‐T through the inhibition of the TNF signaling pathway and the mitogen‐activated protein kinases signaling pathway." (PMID 38156382, 2023). "The CD4+, CD8+ T cells of cows with mastitis expressed significantly higher single-cytokine (TNF-α or IL-2) than those of healthy cows." (PMID 36960295, 2023). "The levels of TNF-α, IL-1β, and IL-6 in whey from cows with mastitis were significantly higher than those from normal cows (p < 0.01)." (PMID 37175449, 2023). "These increased inflammatory mediators such as TNF-α, IL-1ß and IL-6 contributed to the pathogenesis of mastitis." (PMID 35185907, 2022). "Up to the knowledge, Klebsiella pneumoniae promotes the production of the inflammatory cytokine genes IL-6, IL-8, IL-1β, and TNF-α in mastitis already after 6 h." (PMID 35335696, 2022). "In mastitis cases, immunoreactivity was more pronounced for IL-4, IL-6, IL-12, IL-13, IL-17A, TNF-α, and IFN-γ." (PMID 35335696, 2022). "Our results showed that Z-d14CFR enhanced bacterial clearance and reduced neutrophils infiltration and pro-inflammatory cytokines (TNF-α, IL-1β) expression, hence alleviated E. coli-induced inflammation in a murine model of mastitis." (PMID 35563007, 2022). "It is observed that pathogenic activated NF-κB and MAPKs pathways caused overexpression of pro-inflammatory cytokines (IL-1β, IL-6, and TNF-α) in mastitis." (PMID 36145063, 2022). "An in vitro model of M. bovis-induced mastitis showed that the expression of IL-6, IL-8, and TNF-α increased significantly following infection." (PMID 35464378, 2022). "For example, treatment with Morin in LPS-induced mastitis and LPS-induced acute lung injury significant decreased the expression of inflammatory cytokines, including TNF-α, IL-1β, and IL-6." (PMID 35705830, 2022). "Increased concentrations of TNF-α and IL-6 were detected in mice following the induction of mastitis, which indicated an ongoing inflammatory process." (PMID 35337027, 2022). "In mastitis, immune cell activity is mainly regulated by the pro-inflammatory cytokines TNF-α, IL-1β and IL-6, which are typically pro-inflammatory cytokines." (PMID 36090098, 2022). "The mRNA results showed that the contents of inflammatory mediators IL-1β, IL-6, and TNF-α in mastitis tissues were significantly higher than those in the control group (p < 0.01)." (PMID 36355118, 2022). "LPS induces the expression of inflammatory cytokines such as TNF-α, IL-6, and IL-1β in the mammary glands, leading to mastitis in cows." (PMID 34858427, 2021). "The mammary epithelial cells and the resident macrophages are the first line to interact with pathogens at the onset of mastitis, and then, cytophagocytosis is activated, and pro-inflammatory cytokines such as TNF-α, IL-1β, and IL-8 are released." (PMID 35224069, 2021). "The proteins crucial for acute mastitis (IL-18, Il-1β, TNFα, CCL2, CCR1) demonstrate low expression." (PMID 34663465, 2021). "The levels of IL-1β, IL-6, and TNF-α were significantly higher with treatment, indicating that the cell model of mastitis had been successfully established." (PMID 34575880, 2021). "The mRNA and protein expression of TLR4, NF-κB, IL-1β, and TNF-α were up-regulated in mastitis induced by LPS and activated the TLR4/NF-κB signaling pathway." (PMID 34692813, 2021). "One of the major mediators involved in the endotoxic shock that aggravates mastitis is tumor necrosis factor-α (TNF-α), and this inflammatory cytokine is down-regulated by interferon-γ." (PMID 34070499, 2021).
mastitis (continued). "Pathway analysis indicated upregulation of tumor necrosis factor α, heat shock protein response, and p21 related pathways in the response to mastitis in NTK cows." (PMID 33827684, 2021). "Otherwise, rats that received 0.2–20 μg/kg organic selenocompounds during pregnancy developed less severe Staphylococcus aureus-induced mastitis with lower NF-κB activation and TNFα mRNA expression." (PMID 34681720, 2021). "Lactating cows with clinical mastitis and subclinical mastitis showed a marked increase in interleukin (IL)-2, IL-6, IL-1β, and tumor necrosis factor (TNF)-α." (PMID 34827839, 2021). "Analysis of cytokines showed that cows with mastitis significantly increased the levels of IL-1β and TNF-α." (PMID 34222051, 2021). "Previous studies have proved that reducing the production of proinflammatory cytokines, such as IL-1β, IL-6, and TNF-α, can reduce the effect of mastitis." (PMID 33488936, 2020). "The expression of GPR109A, IL-6, IL-1β, and TNF-α in the mammary glands of the dairy cows with mastitis was significantly higher than it was in the glands of the healthy dairy cows." (PMID 32397071, 2020). "LPS can increase the expression of IL-6, TNF-α, and IL-1β in the mammary glands of dairy cows, which leads to the occurrence and development of mastitis." (PMID 32397071, 2020). "Supplementation of the mixture of LAB and yeast decreased the milk concentration of TNF-α, IL-1β and IL-6 compared with mastitis cows, while single use of yeast or LAB was unable to reduce the concentration of those inflammation cytokine concentration." (PMID 31997024, 2020). "Real-time (RT)-PCR showed that, compared with those in the healthy dairy cows, the mRNA levels of IL-6, TNF-α, and IL-1β in the mastitis dairy cows increased significantly." (PMID 32397071, 2020). "A study reported the up-regulation of CXCL8 and TNF-α in E. coli induced mastitis in mammary epithelial cells." (PMID 32927884, 2020). "TNF-α is a major cytokine during the early stages of infection, which in E. coli mastitis is closely related to endotoxin shock." (PMID 32851050, 2020). "The general process of mastitis is characterized by upregulated synthesis of certain pro-inflammatory cytokines, such as TNF-α and IL-1β." (PMID 32117805, 2020). "The expression level reported for IL8 and TNF-α in E. coli induced-mastitis in bovine mammary epithelial cells (BMECs) was much higher than for S. aureus, which is due to the weak Lipoteichoic acid (LTA) induction of TNF-α, or inactivation of NF-κB signaling." (PMID 32927884, 2020). "The findings revealed that chlorogenic acid significantly decreased the production of tumor necrosis factor-alpha (TNF-α), interleukins (IL-1β, IL-6) against lipopolysaccharide-induced mastitis." (PMID 33202871, 2020). "This pathway modulates the expression of many inflammation-related genes (such as inflammatory cytokines TNF-α, IL-1β, and IL-6), especially in mastitis." (PMID 32754201, 2020). "Compared with those in the untreated mastitis group, the somatic cell counts (SCCs) and the expression of IL-6, IL-1β, and TNF-α in the blood and milk were lower." (PMID 32397071, 2020). "In vivo experiments also proved that treatment with sorafenib significantly reduced the levels of TNF-α and IL-6 in breast tissue from mice mastitis, which was further confirmed by histopathology examination." (PMID 31214565, 2019). "TNF-α is a rapid-response proinflammatory cytokine expressed in bMECs and plays an important role in mastitis." (PMID 31612151, 2019). "In this study, TNF-α, IL-6 and IL-1β levels were significantly increased in the LPS-induced mastitis model, and peiminine inhibited the production of TNF-α, IL-6 and IL-1β in a dose-dependent manner." (PMID 30200569, 2018). "Epithelia derived from bovine mammary glands with mastitis evidently express proinflammatory cytokines, such as TNF-α and IL-6." (PMID 29686530, 2018).
mastitis (continued). "LPS can stimulate mammary epithelial cells to produce the inflammatory cytokines TNF-α, IL-1β, and IL-6, which can interact with and regulate the occurrence and outcome of mastitis." (PMID 29849710, 2018). "To study the output of cytokines induced by experimental mastitis, we first measured the levels in milk of IL-6 and TNF-α, both of which are well-established inflammatory markers." (PMID 29988549, 2018). "In a study where sows were experimentally inoculated with intra-mammary E. coli, elevated IL6 and TNF α was measured in inoculated sows 24 h post-inoculation, and was greater in sows that developed clinical signs of mastitis." (PMID 29946552, 2018). "Among them, the production of TNF-α is very important for the synthesis of NO in the mammary tissues stimulated by LPS, and various types of inflammation, including mastitis, are shown to be involved." (PMID 30200569, 2018). "Indirubin inhibited the expression of IL-1β, IL-6, and TNF-α in LPS-induced mouse mastitis in a dose-dependent manner." (PMID 28255203, 2017). "Since activation of TNF-α and its corresponding downstream signaling pathways is mainly employed during initiation and development of mastitis, new therapy with natural products targeting NTF-α activation is very promising." (PMID 28077102, 2017). "We analyzed the anti-inflammatory effects of Se on S. aureus mastitis by determining protein and mRNA levels of TNF-α, IL-1β, IL-6 and IL-10 by ELISA and qRT-PCR, respectively." (PMID 29340029, 2017). "S. aureus-induced mastitis is related to many types of inflammatory cytokines such as TNF-α, IL-1β and IL-6." (PMID 28415707, 2017). "We analyzed TNF-α, IL-1β, IL-6 and IL-10 levels in mouse mastitis model and the mammary epithelial cells by qRT-PCR and ELISA." (PMID 29340029, 2017). "In lipopolysaccharide (LPS)-induced mastitis mouse model, indirubin improves inflammation via inhibiting the production of interleukin (IL)-1β, IL-6, and tumor necrosis factor-α (TNF-α)." (PMID 28525368, 2017). "The level of TNF-α in serum has been reported to be highly elevated in cases of acute clinical mastitis resulting in activation and migration of neutrophils." (PMID 28129375, 2017). "TNF-α plays an important role in the lactating cow’s mammary gland by mediating immune inflammatory responses in mastitis." (PMID 28587645, 2017). "Many investigators have reported higher concentrations of IL-1 and TNF- α in milk and plasma during mastitis potentially mediating local and systemic inflammatory responses." (PMID 28129375, 2017). "In heat-inactivated E. coli challenged bMECs, significant increases of IL-6 and TNF-α gene expression were observed, a finding consistent with a previous study using a different mastitis strain of E. coli." (PMID 27433029, 2016). "In a mouse model of mastitis, IL-6 and TNF-α had high local concentrations in E. coli intramammary infections in wild-type mice." (PMID 26976286, 2016). "Similar to our previously published results, the proinflammatory cytokine expressions (IL-6 and TNF-α) were inhibited by CP treatment following coliform mastitis pathogen challenges (heat-inactivated E. coli as well as endotoxin)." (PMID 27433029, 2016). "The mRNA expression of genes responsible for the inflammatory response (TLR4, LBP, IL-1β, IL-6, IL-8, NF-κB and TNF-α) was significantly increased, consistent with the results of exogenous LPS-induced mastitis by infusion." (PMID 26893357, 2016). "IL-6 and TNF-α are the two most predominant proinflammatory cytokines during the acute phase responses of mastitis." (PMID 27433029, 2016). "An association between clinical mastitis and local production of IL1-beta, IL6 and TNF-alpha is suggested in mammary glands of sows." (PMID 25948480, 2015).
mastitis (continued). "In the present study, CD14, TNF-α, MD-2, IL-1β, NF-κB, and IL-12 gene expression was decreased in tissue affected by mastitis compared to normal mammary tissue, which is consistent with suppression of NF-κB activity and pro-inflammatory cytokine production." (PMID 25706977, 2015). "On the contrary, CD14, TNF-α, MD-2, IL-1β, NF-kB, and IL-12 expression levels were decreased in mastitis tissue with respect to normal tissue." (PMID 25706977, 2015). "Although our study showed significant associations between TNF-α and LTF and immunity to mastitis, the results would be difficult to apply in marker-assisted selection programmes due to interactions with parity." (PMID 23758855, 2013). "The application of the theory of inflamm-aging to interpret the results of this study seems even more justified when we consider the fact that the highest number of statistically significant effects of the TNF-α gene was observed for the duration of mastitis." (PMID 23758855, 2013). "Although the genes relevant to milk production are down-regulated in mastitis, lactoferrin and inflammatory cytokines such as interleukin (IL)-1β, IL-6, and tumor necrosis factor-α are up-regulated." (PMID 24308795, 2013). "The analysis of the effects of the TNF-α and LTF genes in relation to clinical mastitis showed strong associations between gene x parity interaction and MR, EM and DM of the disease." (PMID 23758855, 2013). "The suppression of the nocturnal melatonin surge in innate immune responses to mastitis or surgery incision is inversely correlated with TNF." (PMID 22768337, 2012). "Cytokines, such as tumor necrosis factor α (TNFα), play a role in the immune response and are increased in the serum of cows diagnosed with clinical mastitis." (PMID 22958469, 2012). "Notably, TNF-α, IL-1β, and IL-6 gene expression in lipopolysaccharide (LPS)-challenged mastitis models peaked at three hours, followed by a gradual decline, reaching the lowest levels at 12 h in liver and udder tissue cells." (PMID 40564979, 2025). "Additionally, acute gastrointestinal inflammation directly elevates the levels of proinflammatory cytokines, such as TNF-α and IL-1β, in the bloodstream, which coincides with exacerbated symptoms of mastitis." (PMID 41139776, 2025). "A recent in vitro study demonstrated that Lactobacillus could inhibit the expression of inflammatory cytokines (such as IL-6, IL-1β, and TNF-α), thereby preventing mastitis." (PMID 41011421, 2025). "Additionally, the expression levels of pro‐inflammatory cytokines IL‐6, TNFα, and IL‐1β were markedly increased (P < 0.01), confirming the successful establishment of the mastitis model." (PMID 40552401, 2025). "Moreover, Mansour and Zeitoun have demonstrated that high levels of peripheral cytokines such as TNF-α, IL-6, IL-1β, and IFN-γ cause reproductive failure in buffalo cows suffering from either clinical or sub-clinical mastitis." (PMID 39858163, 2025). "Elevated serum levels of TNF-α are known to induce neutrophil activation and migration, leading to mammary epithelial apoptosis in both bovine and human patients with acute clinical mastitis." (PMID 41295695, 2025). "In an A. viridans-induced mouse mastitis model, a single 25-μg dose of AVPL significantly reduced bacterial loads in the mammary glands (~2-log10), alleviated mastitis-related pathological symptoms, and decreased inflammatory cytokine levels (TNF-α, IL-1β, and IL-6) in mammary tissues." (PMID 40970331, 2025). "Notably, CB treatment in MAC-T cells and mouse mastitis models markedly reduced the expression of IL-1β, TNF-α, and NLRP3, indicating potent anti-inflammatory effects similar to those observed with other natural compounds such as allicin and lentinan." (PMID 40243637, 2025).